ALB (albumin)
Diseases named in the same sentence as ALB in open-access papers (continued):
Sharing a sentence is not in itself a finding about the gene and the disease.
renal failure (continued). "However, when the RRI was added to a kidney failure prediction model that already included the eGFR, age, sex, and albumin-to-creatinine ratio, it improved model fitness but did not improve the discrimination of patients who would develop ESKD when compared to the original model." (PMID 39797308, 2025). "Indeed, serum albumin level < 3.5 g/dL (without diseases interfering with albumin metabolism, such as liver or renal insufficiency) and muscular sarcopenia (<5th percentile of normal upper-arm muscle area) are important markers of poor protein nutritional status." (PMID 26491666, 2015). "However, patients and animals with advanced CKD without nephrosis-range proteinuria also exhibit hypertriglyceridemia and elevated FFA levels, which suggests that increased FFA may be one of the manifestations of renal insufficiency rather than the result of decreased albumin." (PMID 35912916, 2022). "No patients had severe kidney failure (MDRD <15 mL/min); median PTH level was 27.3 ± 18.8 pg/mL (interquartile range 15.8–34.1) and mean albumin-adjusted total serum calcium was 8.9 ± 1 mg/dL." (PMID 30300540, 2018). "In addition, the level of ALB, CRP and ESR were significantly different between patients with and without renal insufficiency." (PMID 31620002, 2019).
Obesity (362 papers, 2005 to 2026). Accumulation of substantial excess body fat. "Obesity was associated with an elevation in renal injury since protein and albumin excretion levels were significantly elevated in obese SSLepR rats vs. lean control rats, with no apparent sex differences." (PMID 41463113, 2025). "The three inflammatory and oxidative markers significantly mediated the association between PBDE85, PBDE99, and general obesity, with lymphatic cell (LC) and albumin (ALB) accounting for 13.31%, 24.0 and 21.79% of the association, respectively (P < 0.05)." (PMID 40350287, 2025). "A connection between obesity and urinary loss of albumin through hyperfiltration as a pathogenic mechanism recognized in focal segmental glomerulosclerosis points to a positive relationship between fat accumulation and albuminuria." (PMID 40566551, 2025). "The experimental data indicates that the pathogenesis of obesity is associated with a decrease in serum albumin levels." (PMID 40453670, 2025). "The combination of hyperinsulinemia and obesity was associated with significant decreases in (p = 0.0001) albumin, albumin/globulin, and IGF-1, and increases in LDH, NO, globulins (p = 0.006)." (PMID 40901060, 2025). "Older age, obesity, a history of previous abdominal surgery, and a decreased postoperative albumin level were independent risk factors for wound complications." (PMID 39535576, 2024). "In conclusion, our study provides evidence for causal associations between obesity and lower circulating levels of nutrients, including magnesium, folate, vitamin A, vitamin C, vitamin E, and albumin." (PMID 39287227, 2024). "Decreased levels of albumin were linked to increased food intake, inflammation, and obesity, potentially due to its ability to bind ghrelin, thus implicating it in the appetite regulation." (PMID 38674857, 2024). "In multivariable analysis, obesity (p = 0.001), shorter operation time (p < 0.001), less blood loss (p < 0.001), normal albumin (p = 0.003), and minor resection (p = 0.046) were significantly associated with achieving TOs." (PMID 38473292, 2024). "Consistent with the literature, risk factors for complications included male gender, obesity, comorbid medical diseases, alcohol consumption, and albumin levels below 3.5 g/dL." (PMID 38774464, 2024). "In CKD patients, plasma leptin levels have been inversely associated with glomerular filtration rate and directly associated with urinary albumin levels as well as age and obesity markers (BMI and waist circumference)." (PMID 36901837, 2023). "For the liver biochemical indicators, obesity mediated the association of dietary fiber with albumin, globulin, total bilirubin, and GGT." (PMID 36684870, 2022). "ALB was reported to be significantly associated with total milk yield, milk fat, and protein percentage in the Holstein cattle and obesity in humans." (PMID 34737760, 2021). "The obtained results indicated that fever, obesity, frequent alcohol consumption, and decreased serum albumin were independent risk factors for the development of DILI in patients with brucellosis." (PMID 34040524, 2021). "The key risk factors predisposing DILI with brucellosis were obesity, regular alcohol consumption, and decreased serum albumin." (PMID 34040524, 2021). "Multivariable logistic regression analyses indicated that obesity, regular alcohol intake, and decreased serum albumin were the independent risk factors of DILI in patients with brucellosis after adjusting for gender, age, and ethnicity." (PMID 34040524, 2021). "Then, overweight and obesity leads to glomerular hyperfiltration, augmented urinary albumin loss, and deterioration of renal function related to a focal segmental glomerulosclerosis." (PMID 32527305, 2020). "The only study to employ a machine learning (ML) approach to identify obesity risk factors in the QBB cohort revealed albumin, uric acid, insulin, and c-peptide as potential risk factors for obesity in Qatar." (PMID 33138081, 2020).
Obesity (continued). "Several risk factors were independently associated with DVT, including obesity, delay to admission, D-dimer > 1.44 mg/L, and reduced albumin level." (PMID 33213498, 2020). "The findings, that reduced albumin is associated with adipose tissue inflammation and predicts T2D, is consistent with chronic low-grade inflammation due to obesity in the development of T2D." (PMID 30774722, 2019). "Reduced serum albumin levels are observed in DN, whereas high serum albumin levels have been reported to be associated with metabolic syndrome, an indicator of obesity and overnutrition." (PMID 26739836, 2016). "Several additions and differences to previous reports of the tCys-obesity association should be noted, including the independence of the association from plasma albumin, which binds most of the cysteine in plasma." (PMID 22984471, 2012). "Female sex; Caucasian race; Morbid obesity (BMI > 30 kg/m2);Protein malnutrition (serum albumin ~2 gm/dL);Recent weight loss (>10% in 6 months)." (PMID 19646226, 2009). "Additionally, IR is often associated with poor nutritional status, including obesity, which further impacts albumin synthesis." (PMID 40729360, 2025). "Factors associated with severity include advanced age, obesity, low serum albumin, and steroid use." (PMID 38515170, 2024). "Likewise, a 1 g/dL decrease in serum albumin level independently conferred an increased mortality risk only within the normal weight to class 1 obesity subgroups." (PMID 39728268, 2024). "Conversely, factors such as chronic inflammation (as indicated by insulin resistance), obesity, smoking, elevated levels of tumor necrosis factor and C-reactive protein, or lower serum albumin levels have been linked with higher serum cystatin C levels, leading to lower eGFRcys according to mGFR." (PMID 39125705, 2024). "Second, how adipose tissue adapts in response to albumin deficiency could provide insights into metabolic regulation and potentially provide strategies for managing obesity-related disorders." (PMID 39123208, 2024). "To test whether the amounts of NEFA bound by human serum albumin were altered in obesity, we isolated albumin from the lipoprotein-deficient serum using affinity chromatography and quantified albumin-bound NEFA." (PMID 37777014, 2023). "Therefore, albumin deficiency prevented any meaningful dysregulation of glucose metabolism when mice were challenged with obesity." (PMID 37432201, 2023). "In addition, the association between obesity and improved prognosis remained significant even after adjustment for serum albumin." (PMID 36983240, 2023). "Therefore, further studies are warranted to elucidate the complex interaction between obesity and urinary albumin as well as the possible mediating role of obesity in the urinary albumin excretion−hypertension association." (PMID 37016928, 2023). "The combination of Fuc-Hp levels suggesting hepatocyte degeneration, albumin levels reflecting liver function, and obesity associated with carcinogenesis may be useful for further stratifying the risk of carcinogenesis among patients with advanced fibrosis." (PMID 36542633, 2022). "Another aspect of the inverse association between albumin and obesity has been recently explored." (PMID 35524905, 2022). "Reduced albumin levels are associated with higher percentage of body fat and adipose tissue inflammation markers such as macrophages, indicating that reduced albumin concentrations might be linked with the inflammatory process and development of obesity." (PMID 33776937, 2021). "In addition, obesity, alcohol abuse, and decreased serum albumin were valuable predictors of the risk of DILI in patients with brucellosis." (PMID 34040524, 2021). "Since obesity is associated with chronic low-grade inflammation, acute phase protein levels, including albumin and transferrin, might be altered." (PMID 29324643, 2018).
Obesity (continued). "Similarly, for obesity, significant associations and risk factors include insulin, c-peptide of insulin, albumin, and uric acid." (PMID 29650030, 2018). "Furthermore, the study found that, in both the absence and presence of inflammation, obesity was associated with a discordant pattern of prealbumin and albumin which was contrary to the patterns seen in other BMI categories." (PMID 30065944, 2018). "In addition, moderate increases in albumin excretion are associated with a variety of other conditions, including obesity, posture, exercise, diet, smoking, gender, puberty, infection, and inflammation." (PMID 28246612, 2017). "However, medical conditions associated with albumin metabolism such as obesity, hyperthyroidism, and nephrotic syndrome, as well as glucocorticoid treatment, are known to affect GA levels." (PMID 26484352, 2015). "However, we observed that obesity was negatively associated with circulating levels of albumin." (PMID 39287227, 2024). "Thus, albumin deficiency did not fully prevent the HFD-induced derangement of all liver health indicators, but based on histology and lipid analyses of liver tissues, it is apparent that albumin deficiency did protect from a substantial proportion of the liver’s obesity-related comorbidities." (PMID 37432201, 2023). "The molecular weights of NfL (61.5 kDa35) and GFAP (50 kDa36) are similar to that of albumin (66.5 kDa), and thus, obesity could also lead to relatively higher loss of these proteins in urine, explaining the decreased circulating levels of NfL and GFAP in the obese." (PMID 35551210, 2022). "However, it remains to be elucidated whether these associations between obesity, oxidative stress, and oxidized albumin are part of the cause or effect of the oxidative process." (PMID 33800425, 2021). "Other variables, including obesity, smoking, biochemical derangements (albumin, calcium, phosphorus, triglycerides, cholesterol), left ventricular ejection fraction, and parathyroid hormone, were not independently predictive after adjustment." (PMID 41267729, 2025). "The study found that obesity, smoking, low albumin concentrations, higher baseline markers of disease activity, and development of immunogenicity were all associated with low drug concentrations and anti-TNF failure." (PMID 40004589, 2025). "Serum albumin concentrations were higher in cats with overweight/obesity in comparison with the normal-weight cats (p < 0.01)." (PMID 39795034, 2025). "Obesity correlates with decreased levels of albumin, albumin/globulin ratio, IGF-1, and glucose/insulin ratio." (PMID 40901060, 2025). "Children with obesity showed increased blood erythrocyte, hemoglobin, total protein, albumin, globulin, prealbumin and triglyceride levels as comparing with normal children (p < 0.05)." (PMID 40551737, 2025). "Statistically significant differences were observed in LSM, CAP, duration, DBP, TC, TG, ALT, AST, ALB levels and the prevalence of obesity among patients at baseline and readmission." (PMID 39498408, 2024). "In patients with elevated CRP levels (>10 mg/L) or low albumin levels (<35 g/L), obesity was found to have a protective effect on survival." (PMID 39795603, 2024). "Variation in laboratory values included alanine transaminase (P < 0.001), alkaline phosphatase (ALP) (P < 0.001), and serum albumin (P < 0.001) with higher values in the group with obesity." (PMID 38911275, 2024). "Previous findings on the correlation between poorer cognitive functioning in older adults and serum albumin levels and obesity‐related parameters are controversial." (PMID 39262164, 2024). "The Covichem score including: obesity, cardiovascular comorbidities, plasma sodium, albumin, ferritin, lactate dehydrogenase and creatine kinase has prediction accuracy of 0.87 (95% confidence interval 0.80–0.91)." (PMID 39436870, 2024).
Obesity (continued). "High age (older than 60 years old), obesity (BMI higher than 30 kg/m2), undergoing ALPPS, and lower postoperative albumin were identified as independent risk factors for post-hepatectomy wound complications." (PMID 39535576, 2024). "This was somewhat surprising given that obesity has been reported to result in glomerular hyperfiltration of albumin and fatty acid." (PMID 39134597, 2024). "Numerous studies show the potential of albumin in the delivery of antibacterial, analgesic, and antifungal drugs, as well as active substances to prevent obesity." (PMID 38255859, 2024). "Pea albumin (PA) has demonstrated positive impacts on reducing obesity and improving glucose metabolism." (PMID 39064674, 2024). "Accordingly, within the underweight and class 3 obesity subgroups, patients with normal and low serum albumin experienced a more comparable course." (PMID 39728268, 2024). "In obese patients, glycated albumin levels can be lower due to higher albumin catabolism and low albumin production rates due to the effects of obesity-related inflammation." (PMID 39091901, 2024). "Low‐carbohydrate diets can improve glucose homeostasis in people with obesity, with decline in serum glycated albumin, MSG, and CV." (PMID 38584275, 2024). "None had changes in clinical serum markers of protein synthetic function (albumin, protein, bilirubin) and only the patient with obesity had impaired fasting glucose suggestive of insulin resistance." (PMID 38722695, 2024). "Factors associated with severe COVID-19 disease included advanced age, obesity, low serum albumin, and home steroid use." (PMID 38515170, 2024). "Participants collected from the National Health and Nutrition Examination Survey (NHANES) database were divided into four subgroups according to their obesity and nutritional conditions, as defined by waist circumference and serum albumin concentration." (PMID 36937935, 2023). "Regarding fundamental conclusions, it is well known that a 75-year-old person with high levels of C-reactive protein, or diminished albumin, or with obesity, or high cholesterol, is unhealthy and has an increased risk of mortality." (PMID 37702598, 2023). "In individuals with obesity and MetS, iron and albumin showed a positive relationship with LDL cholesterol and TG concentrations, respectively (P < 0.05 for all of them)." (PMID 37670399, 2023). "In the multi‐variable adjusted model, the authors observed that older age, higher levels of albumin, overweight/obesity, and hypocalcemia before PD start were independently associated with PD discontinuation and mortality." (PMID 37747660, 2023). "The results provide a characterization of the role of albumin in the processes that lead to metabolic dysregulation and insulin resistance in obesity." (PMID 37432201, 2023). "We tested for the potential metabolic benefits of reducing plasma FFA concentrations in obesity by targeting albumin." (PMID 37432201, 2023). "In individuals with obesity and MetS, albumin showed a positive relationship with TG concentrations (r = 0.49; P = 0.04)." (PMID 37670399, 2023). "Albumin can also be used as a biomarker for many diseases, such as cancer, ischemia, obesity, severe acute graft-vs.-host disease, and diseases requiring monitoring of glycemic control." (PMID 37745114, 2023). "Several factors have been shown to contribute to increased albumin excretion in patients with obesity." (PMID 37238660, 2023). "Conversely, treatment with E. tapos yoghurt (HYT500) in HFD-induced obesity dams propitiously increases the level of total serum bilirubin and albumin, and decreases the level of globulin, albumin–globulin ratio, ALT, AST, ALP, and GGT." (PMID 37415666, 2023). "Obesity and albumin have been recognized as essential parameters for evaluating the nutritional status of patients with cancer." (PMID 36263216, 2022). "The association between low albumin levels and a subclinical inflammatory state was argued to be explaining the link between albumin and obesity." (PMID 35524905, 2022).